CFTR (CF transmembrane conductance regulator)
Diseases named in the same sentence as CFTR in open-access papers (continued):
Sharing a sentence is not in itself a finding about the gene and the disease.
cystic fibrosis (continued). "Cystic fibrosis, an inherited disease found mainly in the Caucasian population, is caused by mutations in the Cystic Fibrosis Transmembrane conductance Regulator (CFTR)." (PMID 31530897, 2019). "CF is an autosomal recessive disease caused by a heterogeneous spectrum of CFTR mutations resulting in deranged function of the cystic fibrosis transmembrane conductance regulator (CFTR)." (PMID 31520190, 2019). "Cystic fibrosis is a hereditary, autosomal recessive genetic disease associated with mutations in the gene encoding a membrane-bound chloride channel named cystic fibrosis transmembrane conductance regulator (CFTR)." (PMID 31013936, 2019). "The most common cystic fibrosis-causing mutation (F508del, present in ~85% of CF patients) leads to CFTR misfolding, which is recognized by the endoplasmic reticulum (ER) quality control (ERQC), resulting in ER retention and early degradation." (PMID 31014000, 2019). "Cystic fibrosis is a genetic disorder caused by defective CF Transmembrane Conductance Regulator (CFTR) function." (PMID 31311920, 2019). "Inherited loss-of-function mutations in the CFTR gene cause cystic fibrosis, the most common life-threatening inherited disease in Caucasians." (PMID 30981209, 2019). "Cystic Fibrosis is the most common life limiting recessive disease in the U.S. and is due to mutations in the CFTR gene." (PMID 31842871, 2019). "Loss-of-function mutations occurring in the gene encoding the cystic fibrosis transmembrane conductance regulator (CFTR) protein cause cystic fibrosis, the most frequent lethal genetic disease in Caucasian populations." (PMID 31311979, 2019). "Cystic fibrosis, the most common inherited disease in Caucasians, is caused by mutations in the CFTR chloride channel, the most frequent of which is Phe508del." (PMID 30158635, 2018). "Cystic Fibrosis is a genetic disorder that arises due to mutations in the Cystic Fibrosis Transmembrane Conductance Regulator (CFTR) gene, which produces a protein responsible for epithelial ion transport." (PMID 30021582, 2018). "More than 2,000 CFTR mutations have been identified so far and at least 336 of these are reported to lead to symptoms characteristic of CF (Cystic Fibrosis Mutations Database report 31 August 2018." (PMID 30581387, 2018). "Since the identification of cystic fibrosis disease in 1938 and the discovery of the causative CFTR (CF transmembrane conductance regulator) gene in 1989, life expectancy of CF patients has increased progressively to more than 40 years in developed country." (PMID 29673202, 2018). "Cystic Fibrosis is the most common fatal genetic disorder, caused by mutations in the Cystic Fibrosis Transmembrane Conductance Regulator (CFTR) gene." (PMID 30004386, 2018). "Mutations in the cystic fibrosis transmembrane conductance regulator (CFTR) protein are key in CF pathogenesis." (PMID 30333828, 2018). "CF is defined as an autosomal recessive respiratory genetic disease induced by mutations in the Cystic Fibrosis Transmembrane conductance Regulator CFTR gene, which encodes important protein in body." (PMID 30627176, 2018). "Cystic Fibrosis is a life-limiting recessive genetic disorder caused by mutations in the CF transmembrane conductance regulator (CFTR)." (PMID 29872446, 2018). "CF is due to loss-of-function mutations of the cystic fibrosis transmembrane conductance regulator (CFTR), reducing the expression or function of this chloride channel at the plasma membrane." (PMID 30568028, 2018). "We also interrogated for mutations in CFTR, gene known to cause cystic fibrosis, since respiratory ciliary dysfunction can occur secondary to CF." (PMID 29444099, 2018). "Cystic fibrosis is caused by a range of different mutations of the CF transmembrane receptor CFTR gene." (PMID 29134356, 2018).
cystic fibrosis (continued). "CF is an autosomal recessive inherited disease affecting several organs but particularly devastating to the lungs, caused by mutations in the cystic fibrosis transmembrane conductance regulator (CFTR) gene." (PMID 30060554, 2018). "Mutations in the CFTR gene are the primary cause of cystic fibrosis, a life-threatening disorder characterised by chronic airway inflammation and infection." (PMID 31435512, 2018). "Interestingly, recent studies suggest a considerable overlap between chronic bronchitis (CB) phenotypic COPD and cystic fibrosis, a common fatal hereditary lung disease caused by genetic mutations of the cystic fibrosis transmembrane conductance regulator (CFTR) gene." (PMID 29849907, 2018). "CF is an autosomal recessive lung disease caused by more than 2000 different mutations in the cystic fibrosis transmembrane conductance regulator (CFTR) gene with approximately 80,000 patients worldwide." (PMID 29540993, 2018). "Cystic Fibrosis due to the ΔF508 mutation of cystic fibrosis transmembrane conductance regulator (CFTR) can be treated with a combination of cysteamine and Epigallocatechin gallate (EGCG)." (PMID 29415993, 2018). "Cystic fibrosis affects mucus producing epithelium including lung and intestine and is caused by mutations in the cystic fibrosis transmembrane conductance regulator (CFTR) gene." (PMID 30111276, 2018). "CF arises from mutations in the cystic fibrosis transmembrane conductance regulator (CFTR) gene that causes sufferers to experience thick, sticky mucous secretions in multiple mucin-producing organs." (PMID 29515516, 2018). "CFTR, a plasma membrane chloride channel with a main role in epithelial cells, is mutated in cystic fibrosis, one of the most frequent genetic diseases." (PMID 30618756, 2018). "Generally, the loss of function or expression of CFTR causes severe symptoms of Cystic Fibrosis, but mutations that reduce function or expression of CFTR cause atypical and mild form of disease." (PMID 30627177, 2018). "Cystic fibrosis is an autosomal recessive disorder caused by mutations in the gene encoding for the Cystic Fibrosis Transmembrane Conductance Regulator (CFTR) protein; it is the most common genetic disorder affecting the Caucasian population." (PMID 29523858, 2018). "In contrast to both asthma and COPD, CF is a single gene disorder that arises from mutations in the cystic fibrosis conductance regulator (CFTR) gene." (PMID 30081920, 2018). "Cystic fibrosis is a relatively common orphan disease caused by loss-of-function mutations in the gene encoding CFTR (cystic fibrosis transmembrane conductance regulator), a tightly regulated anion channel." (PMID 30618775, 2018). "Cystic fibrosis is a fatal hereditary disease resulting from mutation in the CF transmembrane conductance regulator (CFTR) gene." (PMID 29856782, 2018). "It is worth noting that anion channels have been associated with cystic fibrosis, bleeding phenotypes, and inflammatory conditions and may represent valuable therapeutic targets, as demonstrated by clinical use of CFTR modulators." (PMID 28727479, 2018). "CF is caused by mutations in the gene that encodes cystic fibrosis transmembrane conductance regulator (CFTR) protein." (PMID 30018981, 2018). "Cystic fibrosis is an inherited disorder where individual disease etiology and response to therapeutic intervention is impacted by CF transmembrane regulator (CFTR) mutations and other genetic modifiers." (PMID 30581387, 2018). "Cystic fibrosis is an autosomal recessive disease caused by mutations in the gene coding for the protein cystic fibrosis transmembrane conductance regulator (CFTR)." (PMID 30416443, 2018). "Mutations of the CFTR have been shown to cause cystic fibrosis, the most common lethal genetic disease in Caucasians with a hallmark defect in electrolyte and fluid transport affecting multiple organ systems with a multitude of clinical manifestations." (PMID 29449653, 2018).
cystic fibrosis (continued). "CF is an autosomal recessive disease caused by mutations in the cystic fibrosis transmembrane conductance regulator (CFTR) gene, which encodes a chloride channel regulated by adenosine triphosphate (ATP) and 3 ́,5 ́-cyclic adenosine monophosphate (cAMP)." (PMID 29573703, 2018). "Cystic fibrosis is a life-threatening, autosomal recessive genetic disease that affects multiple organs, caused by mutations in the gene encoding the CF transmembrane conductance regulator (CFTR) protein." (PMID 29411170, 2018). "Here, we seek inhibitors of the PDZ protein that facilitates post-endocytic degradation of the cystic fibrosis transmembrane conductance regulator (CFTR): the CFTR-associated ligand (CAL)." (PMID 29472314, 2018). "The molecular basis of CF is a functionally defective ion channel, caused by inheritable mutations in the cystic fibrosis transmembrane conductance regulator (CFTR) gene." (PMID 29360847, 2018). "Cystic fibrosis is an autosomal recessive genetic disease caused by mutations in the cystic fibrosis transmembrane conductance regulator (CFTR) gene." (PMID 30022950, 2018). "CF is caused by mutations in the gene coding for the cystic fibrosis transmembrane conductance regulator (CFTR) protein, which functions as a chloride channel in epithelial cells, macrophages, and other cell types." (PMID 28079883, 2017). "Cystic fibrosis is a genetic disorder caused by mutations in the CFTR gene and is the most common chronic, genetically determined, lethal disease." (PMID 29186897, 2017). "Cystic fibrosis is a complex, systemic, and lethal disorder caused by mutations in the cystic fibrosis transmembrane conductance regulator gene (CFTR)." (PMID 28384265, 2017). "The regulation of CFTR expression appears to be tissue specific and understanding its regulation is important in potential therapies for cystic fibrosis given that many of the disease causing mutations result in lower expression of this critically vital gene." (PMID 29167681, 2017). "Cystic fibrosis is a life-shortening hereditary disease caused by mutations in the Cystic Fibrosis Transmembrane Conductance Regulator (CFTR) gene." (PMID 28545452, 2017). "Cystic fibrosis is a life-limiting autosomal recessive disorder caused by a mutation targeting the Cystic Fibrosis Transmembrane conductance Regulator (CFTR) gene." (PMID 28894437, 2017). "Individuals with cystic fibrosis have an inherited defect in the cystic fibrosis transmembrane conductance regulator (CFTR) gene, causing thickened, dehydrated mucus to form on mucociliary surfaces." (PMID 28349938, 2017). "Cystic fibrosis is a monogenic disease that results from mutations in the cystic fibrosis transmembrane conductance regulator (CFTR) gene that encodes a cAMP-regulated epithelial chloride channel." (PMID 28289476, 2017). "All CF manifestations are caused by mutations affecting the cystic fibrosis transmembrane conductance regulator (CFTR)." (PMID 29376041, 2017). "CF is caused by mutations in the Cystic Fibrosis Transmembrane Conductance Regulator (CFTR) gene coding for the CFTR protein, a member of the ATP-binding cassette transporter family of membrane proteins." (PMID 28785019, 2017). "Cystic fibrosis is the most common fatal genetic disorder, arising due to mutations within the cystic fibrosis transmembrane conductance regulator (CFTR) gene, which alters ion fluxes in mucosal membranes, including the lung airways." (PMID 28325850, 2017). "Cystic fibrosis is a genetic condition caused by abnormalities in the CF transmembrane conductance regulator (CFTR) gene." (PMID 27475719, 2017). "Dysregulated CFTR trafficking is one of the major pathological hallmarks in cystic fibrosis patients bearing missense mutations in the CFTR gene." (PMID 28805732, 2017). "CF, in contrast, is an autosomal recessive genetic disorder caused by defective transcellular ion transport across the Cystic Fibrosis Transmembrane Conductance Regulator (CFTR), which is encoded by the CFTR gene." (PMID 28218655, 2017).
cystic fibrosis (continued). "CF is caused by mutations of the gene encoding for cystic fibrosis transmembrane conductance regulator (CFTR)." (PMID 29333001, 2017). "Deletion of phenylalanine 508 of the cystic fibrosis transmembrane conductance regulator (ΔF508 CFTR) is a major cause of cystic fibrosis, one of the most common inherited childhood diseases." (PMID 28794469, 2017). "Loss of functional CFTR causes cystic fibrosis, an autosomal recessive disorder characterized by the accumulation of thick, sticky mucus, bacterial colonization and chronic inflammation of the airways." (PMID 28455748, 2017). "Cystic Fibrosis is a fatal genetic disease caused by inheritance of mutations in the gene coding for CFTR." (PMID 28640808, 2017). "Cystic fibrosis is caused by mutations in the CFTR gene and is associated with progressive and ultimately fatal infectious lung disease." (PMID 29259090, 2017). "Cystic fibrosis is the most frequent autosomal recessive lethal disorders in the Caucasian population, and results from loss-of-function mutations in the cystic fibrosis transmembrane conductance regulator (CFTR) gene." (PMID 28805732, 2017). "CF is caused by dysfunction of the cystic fibrosis transmembrane conductance regulator (CFTR) protein, an ion channel located on the apical surface of epithelial cells which is responsible for chloride and bicarbonate transport across the cell membrane." (PMID 28509852, 2017). "CF is caused by mutations in the Cystic Fibrosis Transmembrane conductance Regulator (CFTR) gene, whose protein product is involved in the transport of chloride ions across the apical membrane of epithelial and blood cells." (PMID 28187782, 2017). "Cystic fibrosis is the most common life threatening autosomal recessive disorder caused by mutations in the cystic fibrosis transmembrane (conductance) regulator (CFTR) gene." (PMID 28472055, 2017). "Cystic fibrosis is a genetically inherited disease characterized by defects in the transport protein cystic fibrosis transmembrane conductance regulator (CFTR), causing the production of a sticky mucus that stands in the respiratory tract." (PMID 28926942, 2017). "Cystic fibrosis is a heritable, life-shortening disease caused by dysfunction of the CF transmembrane conductance regulator, leading to progressive multisystem organ damage, with lung involvement being the predominant cause of morbidity and mortality." (PMID 29065161, 2017). "CF is caused by mutations in the cystic fibrosis transmembrane conductance regulator (CFTR), a unique ATP-binding cassette (ABC) transporter that functions as a Cl− channel with complex regulation." (PMID 28087700, 2017). "The Cystic Fibrosis Transmembrane Conductance Regulator (CFTR) gene, whose mutations result in Cystic Fibrosis, has been the most replicated gene associated with CRS." (PMID 28400178, 2017). "Cystic fibrosis is caused by the absence or dysfunction of CFTR channel activity, resulting from mutations in the gene." (PMID 28869532, 2017). "CF is caused by mutations in the Cystic Fibrosis Transmembrane Conductance Regulator (CFTR) which is localized primarily in the apical membrane of secretory epithelial cells." (PMID 29403380, 2017). "Cystic fibrosis is a heritable multisystem disorder caused by mutations in the cystic fibrosis transmembrane conductance regulator (CFTR) gene." (PMID 28800122, 2017). "CF is caused by abnormal function of the cystic fibrosis transmembrane conductance regulator (CFTR), a complex protein which functions primarily as a chloride channel, regulating movement of ions and fluid across epithelial surfaces." (PMID 28114922, 2017). "CF is an inherited disease caused by mutations in the cystic fibrosis transmembrane conductance regulator (CFTR) gene leading to altered ion and water transport across apical cell membranes in exocrine glands." (PMID 29112974, 2017).
cystic fibrosis (continued). "Deregulated trafficking of cell surface proteins occurs in human diseases such as cystic fibrosis caused by mutations in CF transmembrane conductance regulator gene, CFTR." (PMID 28540288, 2017). "Cystic fibrosis is an autosomal recessive, life limiting disease, associated with mutations in the gene that encodes Cystic Fibrosis Transmembrane Conductance Regulator (CFTR), a nucleotide and phosphorylation regulated anion channel in epithelia and other cell types." (PMID 28377087, 2017). "CF is an inherited condition caused by mutation of the cystic fibrosis transmembrane conductance regulator (CFTR), which results in the accumulation of mucus (sputum) in patient lungs." (PMID 28536291, 2017). "In order to improve the diagnosis of CF in our country, the present study aims to define a panel of common CFTR gene mutations by sequencing 27 exons of the gene in Ecuadorian Cystic Fibrosis patients." (PMID 29178639, 2017). "The F508 deletion (F508del) in the cystic fibrosis transmembrane conductance regulator (CFTR) is the most common CF causing mutation." (PMID 28855508, 2017). "However, clinical validity – whether recognizing disease-associated variants by sequencing (e.g., of the CFTR locus) predicts the disease (e.g., cystic fibrosis) – is often a more difficult question to resolve than analytical validity." (PMID 28222731, 2017). "CF is caused by mutations in the cystic fibrosis transmembrane conductance regulator (CFTR), which is normally expressed in the epithelial cells of many organs, such as lung and digestive tissues." (PMID 29259702, 2017). "Cystic Fibrosis is an incurable, devastating inherited disease caused by mutations in the CF Transmembrane Conductance regulator (CFTR) chloride ion channel." (PMID 28944753, 2017). "Cystic fibrosis is an autosomal recessive condition occurring among people with European origins, which is caused by mutations in the cystic fibrosis transmembrane conductance regulator (CFTR) gene." (PMID 29232848, 2017). "Cystic fibrosis is caused by mutations in the cystic fibrosis transmembrane conductance regulator (CFTR) gene, which leads to impairments in pancreatic and liver function, and intestinal obstruction." (PMID 28253277, 2017). "Cystic fibrosis is an autosomal recessive genetic disease caused by the loss or dysfunction of the CF transmembrane conductance regulator (CFTR) channel activity resulting from mutations." (PMID 26800689, 2016). "CF is caused by mutations in the gene that encodes the cystic fibrosis transmembrane conductance regulator (CFTR) protein." (PMID 26821237, 2016). "Mycobacterium abscessus infection has been reported in patients with CF, a genetic disease linked to a functional defect of the CFTR (cystic fibrosis conductance transmembrane regulator) chloride channel." (PMID 27906132, 2016). "Cystic fibrosis is a genetic lung disorder, characterized by a deficiency in chloride channel activity, the CF transmembrane conductance regulator (CFTR), resulting in the massive neutrophil granulocyte influx in the airways and mucostasis." (PMID 27738390, 2016). "Individuals with CF have pathogenic variants in both alleles of the cystic fibrosis transmembrane conductance regulator gene (CFTR [MIM 602421)]." (PMID 27996019, 2016). "CF is due to mutations in the cystic fibrosis transmembrane conductance regulator (CFTR) gene, encoding an apical membrane chloride channel that also affects several other epithelial channels or transporters." (PMID 27916834, 2016). "Cystic fibrosis is a common autosomal recessive disorder that affects many body systems and is produced by mutations in the cystic fibrosis transmembrane conductance regulator (CFTR) gene." (PMID 27017198, 2016). "Cystic fibrosis transmembrane conductance regulator (CFTR) is a cAMP-activated chloride channel, mutation of which results in cystic fibrosis, a common fatal autosomal recessive disease." (PMID 27769067, 2016).